GOLGA6A (golgin A6 family member A)
Synonyms: GLP; GOLGA6
Tractability: PROTAC: ubiquitination databases record sites on it.
Gene: Protein-coding gene on chromosome 15 (74,069,857 to 74,082,550, reverse strand). Ensembl gene ENSG00000159289.
Subcellular location (Human Protein Atlas): Vesicles; Centrosome; Nucleoplasm
Gene Ontology:
Molecular function: protein binding
Biological process: Golgi organization
Cellular component: cis-Golgi network; Golgi cis cisterna; Golgi cisterna membrane; Golgi apparatus
Genetic constraint (gnomAD): Loss-of-function variants: 1 observed, 14.52 expected, observed/expected ratio (o/e) 0.0688, 90% interval 0.023 to 0.33. The synonymous counts are far from expectation, so gnomAD's model fits this gene poorly and the ratio says little. Missense variants: 18 observed, 126.44 expected, observed/expected ratio (o/e) 0.14, 90% interval 0.097 to 0.21. Synonymous variants: 6 observed, 44.95 expected, observed/expected ratio (o/e) 0.13, 90% interval 0.072 to 0.26.
Homologues: Orthologues: mouse Golga2 (47% identical), dog GOLGA2 (45% identical), tropical clawed frog golga2 (34% identical), zebrafish golga2 (32% identical), Drosophila melanogaster GM130 (23% identical), Caenorhabditis elegans golg-2 (19% identical), rat Golga2l1 (5% identical). Paralogues in human: GOLGA6B (99% identical), GOLGA6C (99% identical), GOLGA6D (99% identical), GOLGA2 (55% identical), GOLGA8G (54% identical), GOLGA8F (52% identical), GOLGA8S (51% identical), GOLGA8N (49% identical), GOLGA8O (49% identical), GOLGA8Q (49% identical), GOLGA8T (48% identical), GOLGA8K (48% identical), and 6 more.
Diseases named in the same sentence as GOLGA6A in open-access papers:
GOLGA6A is named in the same sentence as 3 diseases in open-access papers, as found by Europe PMC text mining. Sharing a sentence is not in itself a finding about the gene and the disease. The quoted sentences say what the papers report.
tumor (2 papers, 2020 to 2024). "Several genes were also enriched in tumours with an undefined subtype, with the Golgi associated protein GOLGA6A being the most significantly enriched." (PMID 38890455, 2024).
GOLGA6A also shares sentences with these, for which no sentence is quoted: meningioma (2 papers); Headache (1).